AQP4 (aquaporin 4)
Diseases named in the same sentence as AQP4 in open-access papers (continued):
Sharing a sentence is not in itself a finding about the gene and the disease.
multiple sclerosis (continued). "In 31/73 cases (42.5%) with available data, patients were misdiagnosed with multiple sclerosis (MS) by the initially treating physicians, mostly prior to the availability of NMO-IgG/AQP4-Ab testing (83.9%)." (PMID 22260418, 2012). "Multiple sclerosis (MS) and Neuromyelitis Optica (NMO) are immune-related CNS inflammatory diseases that often present with overlapping clinical symptoms, leading to frequent misdiagnosis, particularly in aquaporin-4 seronegative NMO patients." (PMID 40192890, 2025). "In two additional patients negative for both MOG and AQP-4 antibodies, ataxia was sensory and explained by cervical myelitis as part of multiple sclerosis (MS) manifesting temporal relation to NMDAR-E." (PMID 39735552, 2024). "DN NMOSD is a syndrome rather than a single disease, ranging from a (postinfectious) monophasic illness to a more chronic syndrome that can be indistinguishable from AQP4-IgG+ NMOSD or develop into other mimics such as multiple sclerosis." (PMID 37740717, 2023). "As IL-7 has also been implicated in neuromyelitis optica (NMO), a condition marked by antibodies against aquaporin 4 (AQP-4) water channels, IL-7 may protect not only from PTSD and CVD but also from NMO, and the related condition, multiple sclerosis (MS)." (PMID 37218755, 2023). "ON can be the initial event in multiple sclerosis (MS), including clinically isolated syndrome (CIS), in aquaporin-4-IgG positive (AQP4-IgG+) and seronegative neuromyelitis optica spectrum disorders (NMOSD), and in myelin oligodendrocyte glycoprotein-IgG (MOG-IgG+)-associated disease (MOGAD)." (PMID 36908609, 2023). "Therefore, MOGAD is now recognized as a clinical entity distinct from multiple sclerosis (MS) and AQP4 antibody-positive NMOSD (AQP4+ NMOSD)." (PMID 37789888, 2023). "By contrast to patients with radiologically isolated syndrome, of which some will never convert to multiple sclerosis, the pathogenicity of AQP4-Ab in the context of sub-clinical disease, supported treatment in our patient." (PMID 35332817, 2022). "By contrast to patients with RIS of which some will never convert to multiple sclerosis, the pathogenicity of AQP4-Ab in the context of sub-clinical disease (on neuroimaging and optical coherence tomography (OCT)), supported treatment in our patient." (PMID 35332817, 2022). "The discovery of aquaporin-4 (AQP4) has enabled a deeper understanding of the pathological process in NMOSD and made its diagnosis much easier; additionally, the discovery of AQP4 has helped to distinguish NMOSD from multiple sclerosis (MS)." (PMID 34630300, 2021). "Therefore, we compared AQP4 and MOG specific peripheral T-cell response in individuals with AQP4-Ab (n = 8), MOG-Ab (n = 10), multiple sclerosis (MS, n = 8), and healthy controls (HC, n = 14)." (PMID 32625206, 2020). "NMOSD patients were successfully discriminated from a set of healthy volunteers, patients with multiple sclerosis, and AQP4-Ab-negative patients." (PMID 31695085, 2019). "Experiments have shown that anti-aquaporin-4 IgG may play a role in the pathogenesis of NMOSD and can be used to differentiate NMOSD from other demyelinating syndromes such as multiple sclerosis." (PMID 31207529, 2019). "Multiple sclerosis was discriminated from MOG antibody disease and from AQP4 antibody disease with high predictive values, while MOG antibody disease could not be accurately discriminated from AQP4 antibody disease." (PMID 31212763, 2019). "Recent studies proposed that anti-MOG antibody-associated demyelinating diseases were indeed a clinical spectrum in pediatric patients and that their clinical features were different from those of multiple sclerosis and NMOSD with anti-aquaporin-4 (AQP4) antibody." (PMID 28420330, 2017).
multiple sclerosis (continued). "Here, we present a case of aquaporin-4 positive relapsing NMOSD who presented to us with recurrent episodes of paraparesis with LETM and tumefactive lesions of brain on imaging, which enhanced in an incomplete ring like pattern resembling multiple sclerosis." (PMID 27242658, 2016). "It is now clear that NMOSD seropositive for AQP4-IgG is not multiple sclerosis, but an autoimmune disorder affecting predominantly CNS astrocytes (astrocytopathy), and the detection of AQP4-IgG in the serum of patients greatly facilitates the diagnosis of NMOSD." (PMID 34445343, 2021). "In cases of isolated gray matter involvement, the appearance on axial images resembles an H (“H” sign), a finding seen in 30 − 50% of MOGAD patients, with much lesser extent in AQP4-IgG positive NMOSD and absent in multiple sclerosis (MS) patients." (PMID 40327177, 2025). "In multiple sclerosis “mimics”—NMOSD and MOGAD—especially in the individuals that are seronegative for the specific autoantibodies (AQP4 and MOG-Ab), according to researchers, NfL levels do not represent a useful tool in the differential diagnosis." (PMID 40362691, 2025). "Even with the latest NMOSD diagnostic criteria, it remains difficult to differentiate aquaporin 4-IgG (AQP4-IgG)-negative patients with early-stage NMOSD from those with ON, LETM, or multiple sclerosis (MS)." (PMID 31575949, 2019). "Unlike in multiple sclerosis, the autoreactive adaptive immune response in NMO is directed against a known target antigen, namely the water channel protein aquaporin 4 (AQP4)." (PMID 28058717, 2017). "Before the discovery of the aquaporin-4 (AQP4) water channel, clarity was lacking on whether NMO was a distinct illness or a more severe type of multiple sclerosis." (PMID 37175665, 2023). "A 15-year old boy with multiple sclerosis (MS) harbored NMDAR antibodies in CSF at 1:12 (serum negative) < 1 month after the first disease signs; myelin oligodendrocyte glycoprotein (MOG) and aquaporin-4 (AQP4) antibodies were negative." (PMID 32246252, 2020). "We enrolled 49 NMOSD patients [25 aquaporin-4 antibody (AQP4-Ab)–positive, 8 myelin-oligodendrocyte glycoprotein antibody (MOG-Ab)-positive, and 16 seronegative patients], 12 multiple sclerosis (MS) patients, and 15 other noninflammatory neurological diseases (OND) patients." (PMID 30426010, 2018).
Stroke (185 papers, 2007 to 2026). Sudden impairment of blood flow to a part of the brain due to occlusion or rupture of an artery to the brain. "Human studies corroborate AQP4 upregulation in infarcted regions and suggest a potential role for AQP4 polymorphisms and circulating levels as biomarkers of stroke severity and outcome, although larger cohorts and more robust methodological designs are needed." (PMID 40943104, 2025). "The observed associations between AQP4 polymorphisms and stroke outcomes further underscore its potential clinical relevance." (PMID 40564125, 2025). "Loss of AQP-4 polarization is a hallmark of a wide range of brain pathologies associated with stroke." (PMID 40530334, 2025). "Our findings on post‐stroke neuroinflammation revealed a positive association between AQP4 expression and inflammatory cytokines." (PMID 39444081, 2024). "Loss of AQP4 polarization is a hallmark of a wide range of brain pathologies, such as epilepsy, stroke, idiopathic normal pressure hydrocephalus and Alzheimer’s disease." (PMID 38532513, 2024). "Previous research has shown that high MLR is correlated with poor prognosis in stroke patients and increased susceptibility to recurrence in AQP4-IgG-positive NMOSD patients, in contrast to our findings of an association between lower MLR and MOGAD recurrence." (PMID 38259484, 2023). "Studies have confirmed the association of AQP4 in the pathophysiology of cerebral disorders including but not limited to stroke, cerebral edema, traumatic brain injury, Parkinson's disease, epilepsy, and depression." (PMID 36899432, 2023). "Several studies described a relation between AQP4 and inflammation, some of which being also relevant to inflammation-associated formation of cerebral edema after stroke 60-62." (PMID 37554272, 2023). "The bidirectional water transport by AQP4 promotes the formation of cytotoxic cerebral edema in the early stage of an acute stroke, leading to astrocyte swelling and hydrocephalus, causing neuroinflammation and cell death." (PMID 37091130, 2023). "The change of AQP4 expression is associated with many central nervous system (CNS) diseases including epilepsy, edema, stroke, and glioblastoma." (PMID 36203529, 2022). "For instance, AQP4 expression in the blood–brain and blood-spinal cord barriers is associated with brain or spinal cord edema after stroke or spinal cord injury." (PMID 36329045, 2022). "Although these studies have not utilized the preclinical models of CM-induced ICP, the results from AQP4-deficient mice and stroke models suggest the potential utility of targeting AQP4 to reduce ICP in CM patients as well." (PMID 35890028, 2022). "After stroke, AQP4 on the surface of astrocytes cause astrocyte swelling and compression of blood vessels, disrupting the BBB integrity and neurovascular unit homeostasis." (PMID 36159395, 2022). "A loss of perivascular AQP4 similar to that found in experimental stroke—albeit somewhat less pronounced, was observed in the brain of patients that had suffered from mesial temporal lobe epilepsy." (PMID 35518645, 2022). "After stroke, reactive astrogliosis and loss of perivascular AQP4 polarization occur and persist for long time in the peri-infarct area." (PMID 35592320, 2022). "We observed that polarization of AQP4 was significantly disrupted by stroke, with nearly a complete loss of polarization of AQP4 in the region considered." (PMID 33841293, 2021). "Due to specialized features of end-feet, including a high density of orthogonal particle arrays containing AQP4, decreased polarity and increased expression of AQP4 cause edema following stroke." (PMID 32415357, 2020). "This suggests that the attenuated morphological alterations of astrocytes after stroke in Cav-1 KO mice are linked to decreased AQP4 expression." (PMID 32523952, 2020). "Changes in AQP4 activity and expression have been implicated in several CNS disorders, including (but not limited to) epilepsy, edema, stroke, and glioblastoma." (PMID 32111087, 2020).
Stroke (continued). "Levels of AQP4 have been shown to be significantly upregulated in astrocytes post-stroke and are associated with enhanced cerebral edema." (PMID 31011481, 2019). "Dysregulation of AQP4-regulated water flux has been implicated in a number of neurodegenerative diseases, and AQP4 channels play a particularly complex bimodal role in stroke pathophysiology and edema formation." (PMID 27438832, 2016). "Loss of AQP4 from perivascular membranes occurs in epilepsy, stroke, brain injury, and Alzheimer’s disease, but the mechanisms are poorly understood." (PMID 23982198, 2014). "In recent years, a potent neuroprotective agent, erythropoietin (EPO), has been demonstrated to enhance the permeability of astrocyte AQP4 and might directly lower the risk of astrocyte swelling in stroke and other brain disorders." (PMID 39944892, 2025). "Loss of AQP4 protects against early cytotoxic edema associated with stroke." (PMID 37483351, 2023). "Moreover, AQP4 has important implications in hypoxic–ischemic conditions, and studies have shown that loss of AQP4 protects against early cytotoxic edema associated with stroke." (PMID 37483351, 2023). "Furthermore, the protective effect of apelin-13 on BBB post-stroke is significantly associated with the elevated expression of aquaporin-4 (AQP4), which is partly achieved by activating the extracellular signal-regulated kinase (ERK) and PI3K/Akt pathways." (PMID 36034795, 2022). "It has been reported that vasopressin is associated with stroke-related edema and that aquaporin 4 (AQP4), the most ubiquitous water channel in the central nervous system and abundantly expressed in astrocytes, participates in the vasopressin-regulated water reabsorption." (PMID 35360855, 2022). "The loss of AQP4 polarization would impair the clearance efficiency of the glymphatic system, resulting in toxic protein deposition and the induction of cognitive deficits after stroke." (PMID 35592320, 2022). "In the cerebral edema caused by water intoxication and stroke, the brain water content of AQP4 gene knockout rats was significantly decreased, and the prognosis was better, indicating that down-regulation of AQP4 expression can be used as a way of treating cerebral edema." (PMID 35260880, 2022). "Events such as trauma and stroke may alter AQP4 expression, causing abnormal water distribution and disturbed ion balance." (PMID 36119130, 2022). "Targeting the mechanisms underlying AQP4 disassembly and mislocalization could provide a means to modify the reparative response to stroke and brain injury." (PMID 35163040, 2022). "Reduced levels of AQP4 are associated with a number of functional defects, such as impaired hearing and olfaction, and neurological disorders, including edema, epilepsy, and stroke." (PMID 26489685, 2015). "In addition, developing and screening for therapeutic drugs targeting on AQP4 would be valuable in addressing damages caused by stroke, edema, epilepsy and other CNS disorders." (PMID 20885983, 2010). "Moreover, improvements in neurological, motor, and long‐term outcomes after stroke via hybrid stimulation were significantly reversed by AQP4 inhibition, indicating that recovery from functional brain damage after stroke through hybrid stimulation is linked to AQP4." (PMID 39927473, 2025). "Reactive astrocytes, expressing aquaporin 4 (AQP4) and mCRP, were found near large hematomas, which strongly indicates their role in facilitating water entry into the perihematomal area and contributing to brain edema, a major cause of stroke-related mortality." (PMID 40649973, 2025). "Region-dependent changes in AQP4 (increase vs. decrease) have been previously observed after stroke in white vs. grey matter and sub-cellular AQP4 alterations may be linked to accelerated aging and cognitive impairments through its role in perivascular brain clearance of protein aggregates." (PMID 36859364, 2023).
Stroke (continued). "Any reactive astrocytes expressing AQP4 and mCRP were detected in the proximity of large haematomas areas, strongly suggesting that these are key players facilitating the entry of water in the perihaematomal area and contributing to brain oedema, a major cause of mortality in stroke patients." (PMID 32971821, 2020). "AQP4 occupies a central role in the pathophysiology of stroke-related brain edema, acting as both a culprit and a potential cure depending on the injury phase, as thoroughly discussed in previous sections." (PMID 40943104, 2025). "Beyond phosphorylation, other post-translational modifications also regulate AQP4 in the setting of stroke." (PMID 40943104, 2025). "Inhibiting proteasomal degradation with MG132 has been shown to preserve DP71 levels and maintain AQP4 at the endfeet, which improves fluid drainage and reduced brain edema in the post-stroke period." (PMID 40943104, 2025). "Translating animal findings into human stroke pathology has been challenging, but emerging evidence suggests AQP4 is indeed a significant player in human brain edema." (PMID 40943104, 2025). "Post-transcriptional regulation by noncoding RNAs has emerged as an important modulator of AQP4 in astrocytes after stroke." (PMID 40943104, 2025). "Astrocytic aquaporin-4 (AQP4) not only drives post-stroke brain edema progression but also maintains the protective clearance function of the glymphatic system." (PMID 41387988, 2025). "Overexpression of miR-145 or miR-29a/b in stroke models suppresses AQP4, which in turn ameliorates astrocyte swelling and injury, effects that are reversed if AQP4 is knocked out or if these microRNAs are inhibited." (PMID 40943104, 2025). "In autopsied human stroke brains, AQP4 immunoreactivity has been shown to be increased in astrocytes at the peri-infarct border (edema margin) compared to normal tissue or the infarct core." (PMID 40943104, 2025). "Complementarily, pharmacological blockade of AQP4 right after stroke has shown protective effects; treating mice with the AQP4 inhibitor TGN-020 within 1 h of MCAO decreased brain swelling at 24 h and improved long-term functional recovery." (PMID 40943104, 2025). "Then, in the chronic stage after stroke, the global glymphatic function returned to normal as AQP4 expression returned to the baseline levels, while focal glymphatic impairment persisted." (PMID 40837880, 2025). "We conducted a structured literature search to identify studies relevant to AQP4’s role in stroke-related edema, focusing on potential mechanisms, AQP4 functionality, and future treatment avenues." (PMID 40943104, 2025). "Metrics like CSF Influx and AQP4 polarization indicate impaired glymphatic function post-stroke, correlating with increased edema." (PMID 40461672, 2025). "Given its central role in both injury and recovery, AQP4 emerges as a promising yet complex therapeutic target for personalized management of stroke-induced brain edema." (PMID 40943104, 2025). "Aquaporin-4 (AQP4) can be detected in the blood after a stroke using ELISA or other immunoassay techniques, such as Western blotting and mass spectrometry." (PMID 40142325, 2025). "In other words, in the later phase of stroke or in hemorrhagic injuries, AQP4 acts as a “friend” by facilitating the removal of excess fluid from the brain." (PMID 40943104, 2025). "Future directions include real-time imaging of AQP4 function, genotype-stratified clinical trials, and integration of AQP4 modulation with current stroke treatment protocols." (PMID 40943104, 2025). "For astrocytes and AQP4, the reaction of astrocytes was apparent but attenuated 28 days after injury, and AQP4 polarization was significantly reduced at 3 days and successively increased at 14 days and 28 days after stroke." (PMID 40837880, 2025). "High blood pressure variability and sustained hypertension also correlate with 3-month stroke recurrence, likely via blood-brain barrier disruption (eg, oxidative stress, AQP4 upregulation)." (PMID 41370784, 2025).